MYC (MYC proto-oncogene, bHLH transcription factor)
Diseases named in the same sentence as MYC in open-access papers (continued):
Sharing a sentence is not in itself a finding about the gene and the disease.
cancer (continued). "Although the predictions generated in this study should be treated with a degree of caution, these observations would agree with the hypothesis of a cancer susceptibility mechanism mediated by c-MYC germlineoverexpression." (PMID 18190704, 2008). "This study analyzed the hypothesis that variation at 8q24 cis-regulator(s) of transcription could significantly alter germline c-MYC expression levels and, thus, contribute to cancer susceptibility." (PMID 18190704, 2008). "MYC is an oncogene encoding a transcription factor that regulates a number of genes associated with cell cycle regulation and proliferation and plays a vital role in cell metabolism, apoptosis, differentiation, cell cycle progression, and cancer pathogenesis and progression." (PMID 40932956, 2025). "Moreover, we hypothesize that aneuploid cancer cells with a higher number of copies are more susceptible to this blockade of MYC dosage compensation." (PMID 40940795, 2025). "Moreover, MYC causes cancer cells to secrete immune-inhibitory cytokines." (PMID 40290126, 2025). "The capability of BRD4 to influence the transcription of key oncogenes, like MYC, through its association with super-enhancers—large clusters of transcriptional enhancers critical for maintaining cell identity and disease progression, notably in cancer underscores its therapeutic relevance." (PMID 39770515, 2024). "Likewise, overexpression of MYC causes transcriptional dysregulation and cancer pathogenesis." (PMID 38282957, 2024). "Therefore, polyamine-associated cancer cell growth may involve MYC signaling pathway in a wide range of cancers." (PMID 39717382, 2024). "However, further studies are required to interrogate the effect of HLH* EIF3A on MYC-addicted versus merely MYC-expressing cancer cells, as well as determine whether loss of MYC is the sole cause of the proliferation defect." (PMID 37768948, 2023). "Furthermore, it has been shown that the deregulated reduction in MYC protein degradation results in the accumulation of MYC in many cancers, which may be associated with uncontrolled cell proliferation." (PMID 37444499, 2023). "Indeed, MYC oncogene, which resides in 8q24, could represent an ideal candidate to functionally explain the observed cancer risk associations." (PMID 36366788, 2023). "Finally, a retrospective analysis of several clinical studies suggested that elevated MYC expression might be associated with resistance to immune checkpoint inhibitor therapy in metastatic urothelial carcinoma and possibly other cancer types, including TNBC." (PMID 36214609, 2022). "Furthermore, AS has been implicated as a mediator of synthetic lethality in MYC-driven cancers." (PMID 35014671, 2022). "Similarly, MYC activation is indicated as a molecular hallmark of cancer." (PMID 35681732, 2022). "Indeed, in human GWAS, for some loci such as 8q24.21 (containing MYC), different risk SNVs are associated with different risk cancers, although they might ultimately converge toward the same oncogenic mechanism." (PMID 33793571, 2021). "Notably, MYC‐driven cancers were shown to be more susceptible to splicing inhibition, suggesting that the effects of CDK7 on splicing regulation may contribute to its oncogenic role in cancers that rely on MYC." (PMID 34092037, 2021).
cancer (continued). "Similarly, when cribriform Gleason pattern 4 carcinoma maximal diameter was examined as a continuous variable, biopsy specimens with MYC gain or PTEN loss or both alterations had significantly larger cribriform foci (P < 0.0001) than those without these molecular alterations." (PMID 34062284, 2021). "However, careful examination of Cosmic, a public catalog of somatic mutations in cancer, revealed that SNPs in MYC sequence could be detected in a significant fraction of DLBCLs, as reported in BL." (PMID 32102485, 2020). "Besides that, c-MYC is a transcription factor of proto-oncogenes and Hsp70 is a chaperone protein which is involved in cell cycle regulation and differentiation and is a hallmark protein in cancers." (PMID 33551748, 2020). "Both human PVT1 and MYC are located at the 8q24 locus, a well-known cancer-associated chromosome segment and a common and preferred integration site for somatic cell expansion in many cancers, such as prostate, colorectal, breast, ovarian, and cervical cancers." (PMID 31309249, 2019). "Moreover, the correlation between the risk scores from epigenetic signature and ssGSEA scores were analysed and results showed signs of cancer-related hallmarks, e.g. mTOR signalling, G2M checkpoints, MYC targets significantly correlated with the risk scores (FDR q < 0.001)." (PMID 31747912, 2019). "The proximal location between the well-established oncogene MYC and PVT1 in the 8q24 region prompted researchers to analyze whether this lncRNA may somehow regulate or be regulated by MYC, a master regulator of cell growth, proliferation, and differentiation, widely implicated in cancer." (PMID 31781490, 2019). "Since many cancer types harbor mutated MYC, which transcriptionally induces mitochondrial glutaminolysis and leads to glutamine addiction of cancer cells, we speculate that glutamine could become a limiting metabolite that may have a pivotal role in tumor-induced immunosuppression." (PMID 31881671, 2019). "Recently, observations that the well‐known proto‐oncogene MYC controls pre‐mRNA splicing and that MYC‐driven cancers are susceptible to spliceosome inhibition have highlighted the use of pharmacological splicing modulators as promising anti‐cancer agents for MYC‐driven cancers." (PMID 29769258, 2018). "Accumulating evidences indicated that PVT1 can regulate many cancer-related cellular processes, including growth, proliferation, apoptosis, and differentiation, and it contributes to tumorigenesis by participating in DNA rearrangements, encoding microRNAs, and interacting with MYC." (PMID 29348896, 2017). "Thus, by allowing distant enhancers to come in proximity with promoters from ubiquitously expressed genes, disruption of TADs associated with MYC transcriptional control could drive cancer initiation." (PMID 28398229, 2017). "Finally, overexpression of c-MYC, often upregulated through either a stabilization mutation or gene amplification in a wide variety of human cancers, transforms the cells into bona fide cancer cells." (PMID 27198694, 2016). "In addition, it has become clear that a small number of regions associated with many traits harbor multiple independent association signals (a classic example of which is the Chr8q24 region centromeric to MYC, which is associated with many forms of cancer including PrCa)." (PMID 26025378, 2015).
cancer (continued). "While AP1 and MYC have long been associated with cancers, to our knowledge this is the first large scale test of the hypothesis that these TFs bind preferentially in cancer versus non-cancer models for cancer-related genes, and that they cooperate in binding." (PMID 24612742, 2014). "However the observation that activation of MYC and loss RB function are selected for in many cancers, including HCC, would argue against the idea that activation of MYC is sufficient to inactivate RB function and that loss of both RB alleles is merely a passenger effect." (PMID 21573126, 2011). "In this regard, deregulated expression of MYC in cancers could cause constitutive biomass accumulation, rendering cancer cells addicted to nutrients such as glucose or glutamine similar to yeast mutants that were genetically engineered to have constitutive ribosome biogenesis." (PMID 22039435, 2011). "Pathologic conditions that trigger the expansion of immature cells—tissue injury and regeneration, infection, and autoimmune processes—may be associated with cancer because they change the cellular state, now permitting a single oncogene, such as MYC, to initiate tumorigenesis." (PMID 15455033, 2004). "The oncogenic transcription factor MYC is a key driver of the development and progression of various types of cancer, but its intrinsically disordered structure and dependence on protein-protein interactions make it a difficult therapeutic target." (PMID 41900110, 2026). "Although N-Myc has proven to be a difficult therapeutic target, our group and others have previously demonstrated that a small-molecule targeting PP2A, DT-061, drives c-Myc degradation in MYC-driven cancers." (PMID 41707997, 2026). "This work expands the therapeutic landscape for MYC-driven malignancies and highlights proteasome activation as a complementary strategy for targeting structurally disordered cancer drivers." (PMID 42319868, 2026). "Genetic aberrations (e.g. EGFR and MYC amplifications) in cancer cells also lead to dysregulated transcriptional programs which render cancer cells highly dependent upon exceptionally high rates of transcription of genes critical to promoting proliferation." (PMID 41505030, 2026). "Exploiting these MYC‐driven liabilities represents a promising indirect strategy to target MYC in cancer." (PMID 41537447, 2026). "To assess if this link between NPM1 and WNT/MYC signaling was detectable in human cancer, we first examined human tumors from The Cancer Genome Atlas (TCGA)." (PMID 41413654, 2026). "We discuss how the FIR family acts as multifunctional proteins in gene expression dynamics, not only in cancers but also in neural development, in the context of RiBi via MYC-dependent and independent pathways." (PMID 41596295, 2026). "Elucidating these mechanisms is vital for designing targeted therapies against cancers driven by MYC and KRAS." (PMID 41328353, 2026). "The intrinsically disordered MYC proteins are master regulators of cellular growth and function, but when deregulated they become cancer drivers." (PMID 41735282, 2026). "Rather than targeting pharmacologically intractable, disease-driving oncogenes such as MYC, attention has turned to the complexes which govern mRNA transcription in cancer cells." (PMID 41505030, 2026). "The oncogene MYC, deregulated in ~70% of human cancers, has emerged as a central driver of immune evasion and a key contributor to immunotherapy failure." (PMID 41659859, 2026). "Targeted drugs, such as those targeting MYC, have shown efficacy in cancer treatment, and Mettl3 can serve as an upstream regulator of MYC." (PMID 41517663, 2026). "Recent studies have suggested that METTL3 functions as an oncogene by mediating the m6A modifications of EZH2 and MYC, which contributes to the development of cancers." (PMID 41362669, 2026).
cancer (continued). "Synthetic lethal vulnerabilities in MYC‐deregulated tumours describe a state in which MYC‐transformed cancer cells become dependent on specific proteins or pathways for survival." (PMID 41537447, 2026). "As a master regulator of gene transcription, MYC controls multiple biological processes and, when deregulated, drives many of the hallmarks of cancer." (PMID 41537447, 2026). "MYC plays important roles in cell growth and cancer regulatory networks, as well as in longevity and health through the regulation of ribosome biosynthesis (RiBi)." (PMID 41596295, 2026). "This work establishes SMT as a powerful tool to facilitate the drug discovery SAR campaigns and evaluates the therapeutic potential of RUVBL1/2 inhibition in MYC-dependent cancers." (PMID 42017951, 2026). "All three carcinoma populations of different DI showed similar profiles with sCNA, including MYC, GNAS, BRAF amplifications and, as expected, ERBB2 high‐level amplification." (PMID 41144934, 2026). "In aneuploid cancer cells, gene dosage compensation mechanisms involving microRNAs (miRNAs) from the miR-17/92 cluster contribute in regulating MYC expression." (PMID 40940795, 2025). "CDK and combinations can further control cancer growth by inhibiting MYC-amplified cell survival mechanisms and promoting apoptosis." (PMID 39779613, 2025). "In summary, various mechanisms enhance the function of MYC, allowing this powerful transcription factor to promote cancer development in numerous human cancers." (PMID 40732268, 2025). "Unexpectedly, IL-17C also enriched the MYC gene set, a well-known driver of cancer progression frequently overexpressed in HNSCC." (PMID 40974979, 2025). "The pan-cancer analysis demonstrated that AURKA expression heterogeneity was present among urological tumors at different molecular levels, and the positive correlation of AURKA alteration with MYC and E2F pathways was conserved in pan-cancer." (PMID 40718709, 2025). "Analysis of other upregulated cancer pathways also revealed a connection with MYC, reinforcing its role as a master regulator of cellular metabolism, as well as a promoter of mitochondrial biogenesis and energy production." (PMID 41273720, 2025). "Among TFs, bromodomain-containing (BRD)-4 is a promising therapeutic target for regulating the expression of oncogenes such as MYC in multiple cancers, including MM." (PMID 40308607, 2025). "Lastly, given the large number of target genes of master regulators like MYC, future studies should disentangle the relative contributions of splicing programs to the phenotypic changes of cancer cells compared to other regulator-driven molecular programs." (PMID 41101775, 2025). "The PVT1 (Plasmacytoma variant translocation 1) lncRNA is located approximately 50 kb downstream of the MYC proto-oncogene and is frequently co-amplified with MYC in various cancer types." (PMID 40743223, 2025). "EBV+/MYC+ cancers had a greater immune cell population, characterized by elevated macrophage levels (median 12%) and NK/T cells (median 9%)." (PMID 40563566, 2025). "Cancer growth is slowed in a number of preclinical cancer models when MYC expression or activity is removed." (PMID 40290126, 2025). "This positions MYC as a central regulator that links oncogenic signals to cancer splicing factor programs, consistent with prior reports on its role in splicing regulation in cancer." (PMID 41101775, 2025). "Similar dual regulation of pro- and anti-apoptotic genes was observed in BEAS-2B cells infected with Spn reference strain D39 for 16 h, mirroring patterns reported in MYC-driven cancer biology." (PMID 41171083, 2025). "Most miRNAs that directly bind to MYC mRNA are reduced in cancer, such as the let-7 family and miR-145." (PMID 40126351, 2025). "The proto-oncogene MYC is a critical effector of tumorigenesis through regulating cell cycle and apoptosis and is aberrantly expressed in approximately 70% of human cancers." (PMID 40382345, 2025).
cancer (continued). "MYC is among the most frequently dysregulated oncogenes in human cancers, yet remains challenging to target directly in clinical settings." (PMID 40832336, 2025). "To explore enhancer connectome diversity between different cancer types, we first considered the MYC oncogene located on chromosome 8, which is regulated by surrounding tissue-specific enhancers." (PMID 40355593, 2025). "For example, given its role as described in this review for MYC stability, IGF2BP is a promising target for alternative MYC inhibition in cancer treatment." (PMID 40126351, 2025). "In the cancer, cell death, and cellular function network, 19 mRNAs and 19 proteins were differentially expressed, including MYC, PSMB9, and RPL9." (PMID 40700094, 2025). "Together, these studies provide compelling preclinical evidence that dual targeting of MYC signalling, and ATR-mediated checkpoint control can selectively collapse the replication-stress tolerance of MYC-overexpressing cancers." (PMID 41561634, 2025). "More particularly, the MYC oncogene has historically been recognized as a ‘most wanted’ target for cancer therapy, since it is deregulated in most, perhaps all, human cancers." (PMID 40955778, 2025). "We stratified cell lines by MYC Target V1 signature enrichment (top and bottom 35%) from the Cancer Cell Line Encyclopedia and compared the drug IC50s between two cell line groups." (PMID 41025936, 2025). "MYC plays, instead, a crucial role in the development and progression of ARMS, a highly aggressive pediatric cancer characterized by its association with specific fusion proteins, primarily PAX3-FOXO1 or PAX7-FOXO1." (PMID 40076599, 2025). "In the correlation analysis with hallmark pathways, the AURKA expression had a strong and positive correlation with pathways such as MYC targets, G2M checkpoint, and E2F targets in the majority of cancers (correlation coefficients > 0.6)." (PMID 40718709, 2025). "These signalling pathways funnel through MYC to execute the transcriptional programmes that eventually lead to the uncontrolled proliferation of cancer cells." (PMID 39972241, 2025). "Recent findings indicate a compelling bidirectional relationship between MYC and the molecular clock, likely disrupted in various cancers." (PMID 39812541, 2025). "Since PKM2 facilitates the last stage of aerobic glycolysis, whereas PKM1 facilitates oxidative phosphorylation, MYC promotes glycolysis in cancer cells." (PMID 40290126, 2025). "A recent study showed that decreased eIF4A1 levels suppress lymphomagenesis in murine MYC-driven lymphoma, suggesting that eIF4A1 is a viable target for cancer therapy." (PMID 39779613, 2025). "PRMT5 is required for survival of MYC-driven cancer cells, and has been extensively studied as a potential cancer therapeutic target." (PMID 40326560, 2025). "MYC, a key oncogenic transcription factor, plays a central role in the metabolic reprogramming of cancer cells by activating the expression of various metabolic enzymes." (PMID 39980052, 2025). "Cancer cells may adapt to MYC-targeted therapies, particularly in HR-deficient backgrounds, by engaging compensatory DNA repair pathways, activating alternative transcriptional programs, or modulating checkpoint responses, potentially reducing the efficacy of MYC–DDR combinations." (PMID 41561634, 2025). "Researchers are exploring combination therapy that inhibits both MYC and mTOR to improve treatment outcomes for MYC-driven cancer." (PMID 39779613, 2025). "MYC multifaceted capacity to induce replication stress makes it key in the induction of genomic instability observed in cancer cells." (PMID 41561634, 2025). "In cancer, MYC-driven increases in DNA repair gene expression are typically associated with resistance to DNA damaging agents." (PMID 40647552, 2025). "LDHA is essential for increased glycolysis and oncogenic functions in cancer cells and is a transcriptional target of the oncogene MYC, which provides molecular regulation for the Warburg effect." (PMID 40734168, 2025).